CD4 (CD4 molecule)
Diseases named in the same sentence as CD4 in open-access papers (continued):
Sharing a sentence is not in itself a finding about the gene and the disease.
infection (continued). "Thus, it is notable that anti-ICOS administration from day 3 of infection, after initial CD4+ T cell priming and differentiation events, led to impaired IL-10 production by parasite-specific CD4+ YFP+ T cells." (PMID 26459508, 2016). "Moreover, 5 days post infection, mature Gag products were lower in CD4+ T-cell lysates infected with C-Env viruses, which is inconsistent with a defect in viral release." (PMID 27598717, 2016). "However, administration of that same serum to CD4+ T cell-sufficient naive mice at the time of primary infection decreases the infectious burden and shortens the course of infection compared to mice that do not receive immune serum." (PMID 27600502, 2016). "However, IFNγ-producing CD4+ cells most likely act in the later stages of primary infection, during the adaptive phase of the response, since death in CD4-deficient neonates is delayed until ≥15 days post infection." (PMID 28119902, 2016). "Aubert and colleagues demonstrated that adoptive transfer of naive lymphocytic choriomeningitis virus (LCMV)-specific CD4+ T cells into mice transiently depleted of CD4+ T cells at the time of LCMV clone 13 infection results in the generation of LCMV-specific antibody responses." (PMID 26865713, 2016). "We also compared the frequencies of splenic CD4effector (CD4+CD44highCD62Llow) cells in mice infected 20 days earlier, and we also observed that upon infection, CD4+ T cells expressing IFN-γ and/or TNF can be detected without ex vivo restimulation, as previously reported." (PMID 27128676, 2016). "This conclusion is in keeping with studies of CD4+ T cell responses following L. major and Salmonella infection, that collectively suggest that continued re-exposure of pre-existing memory and / or effector CD4+ T cells to persistent antigen is important for the maintenance of effector function." (PMID 27658046, 2016). "Thus, drugs with CD4 down-regulatory activity can inhibit virus entry by reducing the CD4 receptor density that is required for infection." (PMID 27540531, 2016). "Histological examination showed that the increase in skin CD4+ T cells persisting at memory post infection or DNFB sensitization resulted from an increase in the proportion of hair follicle-associated clusters combined with an increase in the average number of T cells within a given cluster." (PMID 27160938, 2016). "Previous experiments showed that albeit CD4+ cells are involved in the immune response induced during S. suis infection, their activation status seems to be compromised and their role in controlling infection limited." (PMID 27905502, 2016). "Notably, IL-10 exerted quantitatively stronger regulatory effects on innate and CD4+ T cell responses during primary and secondary infections, respectively." (PMID 27630165, 2016). "CCR5-dependent homing of CD4+Foxp3+ Tregs at infectious sites in parasitic pathogen infection models has been shown to promote pathogen persistence by regulating the magnitude of pro-inflammatory responses and the equilibrium between IL-17+CD4+ Th17 and CD4+Foxp3+ Tregs." (PMID 27439902, 2016). "Moreover, the time from infection to reaching a CD4 cell count <500 cells/mm3 has been estimated to be relatively short." (PMID 27129591, 2016). "Importantly, miR-182 and its family member, miR-183 were significantly co-regulated in CD4+ T cells isolated from vaccinated mice protected at day 6 after a subsequent intravaginal Cm infection." (PMID 27556515, 2016). "However, infection did begin to resolve during the time CD4+ T cells were functionally depleted (i.e., day 21)." (PMID 27600502, 2016). "It was found that after 4x, compared to 1x, exposures there were major changes in the cell populations within the skin site of infection such that eosinophils, macrophages, dendritic cells (DCs), neutrophils, mast cells, CD4+ T cells and keratinocytes were all increased after 4x infections." (PMID 27505056, 2016).
infection (continued). "Consistent with this, CD38+ CD4+ T cells displayed significantly reduced levels of both pSTAT1 and pSTAT4 compared to CD38- CD4+ T cells (p = 0.016 and p = 0.031 prior to infection, and p = 0.0002 and p = 0.0002 post-infection for pSTAT1 and pSTAT4, respectively)." (PMID 27662621, 2016). "Moreover, adoptively transferred CD8+ and CD4+ immune T cells entered the CNS of C57BL/6 RAG1-/- mice with advanced infection and both eradicated the bacteria." (PMID 27875529, 2016). "Here we found that HCV monoinfected IDU had lower CD4+ T cell telomere lengths than healthy donors at the first timepoint in infection that we analysed, suggesting that HCV on its own may have an effect on immune senescence." (PMID 27034702, 2016). "Despite exhibiting comparable phenotypes, CD4+ YFP+ GFP+ T cells from the liver and lung produced significantly larger quantities of IL-10 than their splenic counterparts, showing that the CD4+ YFP+ GFP+ T cells exert graded functions in distinct tissue locations during infection." (PMID 26459508, 2016). "Furthermore, CD4+ T cells proliferate more in p110γ-KD than WT mice at late time-points of infection, which can be likely explained by the continuous presence of virus in the p110γ deficient situation." (PMID 27030971, 2016). "Whilst these subsets develop from the same CD4+ T lymphocyte precursors, their diverse phenotype and function mean that their presence and relative proportions can greatly influence the outcome of infection." (PMID 27507428, 2016). "Moreover, adoptive transfer of immune CD4+ T cells still protects approximately 60% of C57BL/6 RAG1-/- mice when applied later in advanced infection when the bacteria start to rise." (PMID 27875529, 2016). "•Dysfunctional glucose metabolism in CD4+ T cells and monocytes is a hallmark of HIV+ infection." (PMID 27211546, 2016). "Immune cell genital tract infiltration following infection in CD4-depleted IFN-γ−/− mice." (PMID 27600502, 2016). "During MuLV-infection CD19+ DCs were distinguished from conventional B cells by exhibiting mature APC phenotypes, higher susceptibility to MuLV infection, enhanced proliferation and IDO expression dependent on CD4 T cell interactions." (PMID 27168185, 2016). "None of these animals developed disease whether receiving CD8+ or CD4+ T cells and survived the infection." (PMID 27875529, 2016). "During this infection the immune response relies on CD4+ T lymphocytes (TLs) and it may be affected by the interaction of HAV with its cellular receptor (HAVCR1/TIM-1) on T cell surface." (PMID 27578921, 2016). "Notably, α-IFNAR treatment reduced the proportion and number of infection-induced effector CD4 T cells co-expressing both T-bet and Blimp-1-eYFP by >30%." (PMID 27732671, 2016). "BCG-infected DCs produced significant levels of IL-12 after infection with BCG indicating that BCG-infected DCs could contribute significantly to the induction of a CD4+ Th1 immune response." (PMID 27530534, 2016). "Could the frequency of a particular CD4 T cell specificity serve as a predictor of later B cell responses, or perhaps a response more dedicated to protection from infection in distal tissues?" (PMID 27329272, 2016). "Since we previously showed that the defect of virus replication in UNG2-depleted human CD4-positive cell lines was related to a defect in the RT process, we quantified total viral DNA reverse transcripts 7 h after infection of PBMCs with viruses produced in UNG2- or RPA32-depleted cells." (PMID 27068393, 2016). "Conversely, infection of SupT1 cells with a virus that overexpresses the CD4 receptor, pNL4–3 F2A-CD4-Flag ΔVpu Nef demonstrated that Nef is capable of reducing total cellular CD4, which is consistent with previous reports of Nef-mediated degradation of CD436." (PMID 27841315, 2016). "However, cross-clade neutralization strongly correlated with high viral load as well as with low CD4 T cell counts, subtype-C infection and HLA-A*03(-) genotype." (PMID 26766578, 2016).
infection (continued). "There was a consensus among the researchers we interviewed that understanding the characteristics of the HIV ‘reservoirs’ in the body, as well as the ways they related to both latent (whereby the virus remains in the resting CD4+ T cells) and active infection, was a key research priority." (PMID 27137204, 2016). "Noticeably, self-cured P. yoelii 17X infection resulted in PD1 expression in CD4+ and CD8+ T cells." (PMID 27900319, 2016). "Multivariate analysis revealed that the duration of infection did not affect the association between the presence of anti-Tat IgM, high CD4+ T cell counts and low viral load and between the presence of anti-Tat IgA, CD4+ T cell loss and high viral load." (PMID 27450538, 2016). "Following activation, CD8 T cells can migrate to sites of infection and kill infected cells, whereas CD4 T cells contribute to the elimination of pathogens by trafficking to infected tissues and providing help to innate immune responses, B cells, as well as CD8 T cells." (PMID 28003809, 2016). "The number of each T-cell population in the neuropil varied during the progression of the infection at both anterior and posterior levels, and in most instances the number of CD4+ T-cells and CD8+ T-cells was approximately 2-fold higher at the posterior than at the anterior level." (PMID 28002454, 2016). "We hypothesized that lipoproteins expressed in M. tuberculosis and M. bovis BCG (MTB complex), but not in M. smegmatis, are responsible for the increased HIV infectivity of CD4+ T cells following MTB complex infection of PBMC ex vivo." (PMID 26807859, 2016). "Of note, the total Plasmodium infection-induced effector CD4 T cell compartment can be distinguished from irrelevant (naïve) CD4 T cells via published surrogate marker approaches that monitor conformational changes in CD11a and upregulation of CD44 on CD4 T cells following infection or vaccination." (PMID 27732671, 2016). "However, as importantly, we found that ICOS also plays a role in controlling IL-10 production by CD4+ YFP+ T cells during infection." (PMID 26459508, 2016). "As in Jurkat cells, CIB1- and CIB2-depleted CD4+ T-lymphocytes displayed a significant decrease in susceptibility to infection when challenged with HIV-1-enveloped particles but not with VSV-G-enveloped particles." (PMID 27489023, 2016). "This impairment in virus replication in shUNG2-transduced HeLa-CD4 cells (red curve and red bars, respectively) was observed as soon as 2 days post-infection and remained significant 4 and 8 days post-infection compared to shLuc-transduced HeLa-CD4 control cells (black curve and black bars)." (PMID 27068393, 2016). "Importantly, we found that co-culture of miR-155 inhibitor and mimic transfected BMDC or miR-155−/− BMDC with CD4+ T cells isolated at day 12 post infection from Cm infected mice resulted in significant modulation of Ag-specific IFN-γ production." (PMID 27556515, 2016). "Therefore several exogenous signals, including CCL19 and mDC, can facilitate the efficient, direct infection of resting CD4+ T-cells and establishment of latency." (PMID 27383184, 2016). "Thus, reactivating malaria infection–induced Ag-experienced memory CD4+ T cells appear specifically programmed to rapidly become differentiated IL-10–producing cells following challenge infection." (PMID 27630165, 2016). "In summary, we showed that one dose of 4C-Staph/T7-alum vaccine elicits a fast and efficacious protection against S. aureus systemic as well as peripheral infection through the induction of vaccine-specific functional antibodies, CD4+ effector T cells, and IL-17A." (PMID 26812180, 2016). "Finally, mast cells and basophils rectruited at the site of HIV infection can directly contribute to the spread of the infection by acting as virus reservoir and mediating trans-infection of CD4+ T cells, as recently demonstrated." (PMID 27822141, 2016).
infection (continued). "Thus, it is likely that the presence of these CD4 T cells is helping to dampen inflammatory mediators in the young lungs during infection, especially since these mice have very low levels of albumin in their lungs indicating minimal lung damage." (PMID 27177221, 2016). "Furthermore, B. fragilis has been shown to promote growth of gut-associated lymphoid tissue by producing polysaccharides that can activate CD4+ T cells which assist in directing lymphocytes to sites of infection." (PMID 27252696, 2016). "For the delivery sub-group, infection at delivery was associated with a significantly diminished level of IL-10 in response to both PHA and DBL-5, as well as a significantly reduced frequency of DBL5-specific IFN-γ-producing CD4+ T cells in MI versus UI." (PMID 27653505, 2016). "Modulations in the frequencies of CXCR3+ CD4+ T cells were observed upon infection." (PMID 27509048, 2016). "Conversely, it remains unclear how viral replication and systemic immune activation – both particularly high during PHI – may shape effector CD4 T-cell responses, and whether HIV-specific CD4 responses contribute to the immune activation in early infection." (PMID 27746782, 2016). "Neither IL-27 nor ICOS played a role in the development of parasite-specific CD4+ YFP+ T cell responses during infection, implying that these pathways specifically modify the induction of IL-10 expression, rather than modifying the initial development of the Th1 response." (PMID 26459508, 2016). "ART probably had little effect on the evolutionary dynamics of SPVL in Uganda because it only became available in 2004 and is initiated at relatively late stage infection (CD4 < 250 cells/mm3 from 2004 to January 2011, and at < 350 cells/mm3 from February, 2011 to the time of writing, August 2016)." (PMID 27815945, 2016). "In HIV-infected CCL19-treated resting CD4+ T cells, treatment of cells prior to infection with the inhibitors of PI3K, LY294002 and Wortmannin, significantly reduced HIV integration as measured by Alu-LTR PCR, and reduced the levels of 2-LTR circles back to the level of unactivated cells." (PMID 27459960, 2016). "This inefficient priming of naive CD4+ RTEs, in combination with local exhaustion and increased apoptosis of T cells, suggests that there is minimal replenishment of the T cell pool during on-going infection, thus limiting effector T cell responses." (PMID 27658046, 2016). "While it seems intuitive that deteriorating CD4+ counts are associated with worse mucosal barrier function, other reasons for elevated BDG may include potential colonization or subclinical infection with Candida spp." (PMID 27752257, 2016). "The overrepresentation of Foxp3+ cells within the CD4 SP compartment seen during infection, conjointly with a diminished cell death, reveal that this population is more resistant to apoptosis compared to the Foxp3−CD4 thymocytes, but not enough to prevent the tTreg loss in absolute numbers." (PMID 26745276, 2016). "Finally, we observed no substantial differences in the cellularity of the spleen, or bulk CD4+ T cell or B-cell numbers, in WT versus Ifnar1-/- mice during PcAS infection, Py17XNL infection, or in un-infected mice." (PMID 27812214, 2016). "Both vaccination and infection induced a rise in E. chaffeensis-specific antibody titers and a significant Th1 response in peripheral blood as measured by E. chaffeensis antigen-dependent CD4+ T cell proliferation and IFNγ production." (PMID 26841025, 2016). "At later time points, infection proceeded with robust viral replication and evident CD4+ T cell depletion, except in one mouse that showed complete suppression of viral replication and preservation of CD4+ T cell count." (PMID 27128948, 2016). "However, the number of activated CD4+ T-cells decreased during the evolution of Lb and La infection." (PMID 27073297, 2016).
infection (continued). "This immune evasion mechanism might be relevant to the establishment of a chronic phase of infection and relies on the induction of regulatory CD4+ Foxp3+ T cells that actively suppress CD8+ T cell priming and curtail their functionality." (PMID 27332899, 2016). "Although CD8+ T-cells can eliminate infected cells via contact mediated lysis, and CD4+ T-cells contain infection by secreting IFN-gamma in mice, it is unknown whether these cells exert independent, additive, or synergistic control of HSV-2." (PMID 27285483, 2016). "We show that infection of mice with the chronic gastrointestinal helminth Heligmosomoides polygyrus drives rapid polyclonal expansion of Foxp3+Helios+CD4+ thymic (t)Tregs in the lamina propria and mesenteric lymph nodes while Foxp3+Helios−CD4+ peripheral (p)Treg expand more slowly." (PMID 26286232, 2016). "The importance of CD4+ T cells is evident in persons with HIV-1-associated depletion of CD4+ T cell numbers and function; while not on antiretroviral therapy, these individuals are at > tenfold greater risk of progression from infection to disease." (PMID 27183822, 2016). "IL-2-/IFN-γ co-expressing CD4 T cells decreased during the course of infection." (PMID 27760221, 2016). "Of note, only IP-10 levels measured less than 24 months before infection had such an impact: IP-10 levels measured between 24 and 60 months before infection did not influence the rate of CD4 T-cells loss." (PMID 27509048, 2016). "In HIV monoinfected persons, HIV-specific, IL-17A-producing CD4+ T cells have been detected in early infection and have been proposed to be virus-specific T cells aberrantly primed as a result of microbial translocation due to HIV-related depletion of gut CD4 T cells." (PMID 27124305, 2016). "Effective ART often helps control the multiplication of HIV in infected patients and increases the count of CD4 cells, thus, prolonging the asymptomatic phase of infection, slowing the progression of the disease, and also helps in reducing the risk of transmission." (PMID 27054050, 2016). "The viability of infected p24(+) CD4 T cells was similar in R3A and R3A-5/6AA infection." (PMID 27026376, 2016). "Latency can be established in vitro by direct infection of resting CD4+ T-cells in the presence of stimuli, including the chemokine CCL19; high viral titres with or without spinoculation; or culturing T-cells in contact with myeloid dendritic cells [mDC,] or endothelial cells." (PMID 27383184, 2016). "Both CD4+ and CD8+ naive T-cell TREC contents declined biphasically, with a rapid loss during the first year and a much slower loss during the chronic phase of infection." (PMID 27010200, 2016). "Therefore, separate and distinct populations expressing HIV-1 from both integrated and unintegrated templates is a common phenomenon when resting CD4 T cells are stimulated several days after infection." (PMID 26728316, 2016). "Thus, we examined the cytolytic potential of CD38+ CD4+ T cells by measuring their intracellular expression of perforin and granzyme B by flow cytometry both prior to and at peak infection." (PMID 27662621, 2016). "Similar to the CD38+ CD4+ T cells circulating in vivo in the P. falciparum experimental infection model, this in vitro generated CD38+ CD4+ T cell population showed a phenotype associated with recent activation and cytotoxic potential at both protein and mRNA levels." (PMID 27662621, 2016). "We have addressed the impact of elevated IL-10 production during secondary infection in shaping anamnestic immune responses and demonstrate that IL-10 may play an important role in regulating reactivation of memory CD4+ T cells." (PMID 27630165, 2016). "In accordance with the kinetics of pathogen control, the relative and absolute numbers of Lm OVA-specific CD8+ T cells were significantly increased in CD4-Cre A20fl/fl mice at day 7 after infection with Lm OVA, i.e. the peak of the primary CD8+ T cell response." (PMID 28004776, 2016).